CD4 (CD4 molecule)
Diseases named in the same sentence as CD4 in open-access papers (continued):
Sharing a sentence is not in itself a finding about the gene and the disease.
myocarditis (continued). "Although most of these disease models involve the mediation of CD4 T cells and/or antibodies, the role of CD8 T cells is unclear, and it has been a challenge to ascertain the antigen specificity of cardiac-reactive T cells in the causation of myocarditis for routine investigations." (PMID 37830560, 2023). "Therefore, differentiating between acute and chronic forms of myocarditis based on the CD4+/CD8+ ratio may be a viable option." (PMID 37568452, 2023). "In addition, NG52 could inhibit the activation and differentiation of CD4+ T cells from mice with myocarditis and patients with myocarditis in vitro." (PMID 37266437, 2023). "Thus, besides necrosis and oedema, histological samples of ICI-induced myocarditis consist of mononuclear cell infiltration: mixed CD4+ and CD8+ lymphocytic populations (usually with the predominance of cytotoxic T cells), macrophages (CD68+), and occasionally CD20+ B cells." (PMID 36142866, 2022). "Moreover, except the cases with active myocarditis (patients 1 and 2), giant cell myocarditis (patients 3 and 14), and one case of DCMi (patient 9), CD4+-T-cell-to-CD8+-T-cell ratio was ≥1, suggesting a predominantly autoimmunological origin of the observed inflammation." (PMID 35805941, 2022). "Additionally, CD4+ cells were lower in meningoencephalitis than in myocarditis and milder forms." (PMID 34591866, 2021). "However, the crosstalk between miRNAs and CD4+ T cells in myocarditis is elusive." (PMID 32269577, 2020). "Here, we review the role that T cell CD4+ subsets, myeloid subclasses including myeloid-derived suppressor cells may play in the immunopathogenesis of Chagas disease with special focus on myocarditis, by comparing results obtained with different experimental animal models." (PMID 29545782, 2018). "Therefore, the severity of the myocarditis is due to an accumulation of pathogenic IFN-γ-producing CD4 T cells rather than the higher production of IL-27." (PMID 29033934, 2017). "We believe that suppressive mediators, such as IL-27, are secreted in the later stage of the disease as an attempt of counterbalancing the pathogenic IFN-γ-producing CD4 T cells rather than being a causative factor directly associated with the severity of myocarditis." (PMID 29033934, 2017). "Furthermore, IL-10-secreting CD4+ cells may represent Tr1 T regulatory cells, which can suppress myocarditis induction in CVB3 infected wild-type female mice through inhibition of autoimmune T cell activation." (PMID 24816846, 2014). "With respect to CVB3-induced myocarditis, we demonstrated that both i.v. application of MSCs and of CardAPs resulted in an induction of Tregs, whose protective effects in myocarditis have been consistently demonstrated and in a raise of splenic apoptotic CD4+ and CD8+ T cells." (PMID 23853610, 2013). "Lu’s research found that in myocarditis, both glycolysis and PGK1 expression are elevated in cardiac CD4+ T cells and Th17 cells." (PMID 40356915, 2025). "Spacer also unexpectedly revealed that CD4+ T cells, though fewer in numbers, are more responsive than CD8+ T cells in the heart during myocarditis." (PMID 41332779, 2025). "A repeat biopsy on day 32 of steroid treatment revealed a mixed population of CD4+ and CD8+ T cells along with numerous histiocytes/macrophages, consistent with chronic smoldering myocarditis." (PMID 41373794, 2025). "While the cMy-mOva model of myocarditis relies on CD8+ effector T cells, the experimental autoimmune myocarditis (EAM) model in BALB/c mice utilized in research is triggered by CD4+ T cells." (PMID 39039301, 2025). "Patients with myocarditis and DCM displayed increased numbers of CD4+Th17+ T cells, which in turn produced higher amounts of Th17-related cytokines (IL-6, TGF-β, IL-23)." (PMID 39817455, 2025). "Th17 cells are a subset of CD4+ T-cells, which themselves are important inflammatory mediators in ICI-related myocarditis, and play a pro-inflammatory role by secreting inflammatory cytokines." (PMID 38236243, 2024).
myocarditis (continued). "The relevance of other T helper subtypes has been more debated than Th17 cells, despite CD4+ cells being known to be fundamental to myocarditis pathogenesis, as the treatment of EAM rats with anti-CD4 antibodies blocks the development of the disease." (PMID 39768171, 2024). "Second, LIPUS inhibited the differentiation of CD4+ T-cells, reduced the infiltration of Th17 cells into the CD4+ T-cell subset in ICI-related myocarditis, and increased the ratio of Treg cells, thereby alleviating inflammatory responses." (PMID 38236243, 2024). "EMB from patients with EBV myocarditis typically reveals lymphocytic infiltration, consisting of predominantly CD8+ T cells but also CD4+ T cells." (PMID 38464847, 2024). "Mice with myocarditis corresponded with significantly higher numbers of CD8+ cytotoxic T lymphocytes, Th17 cells, and CD4+ T cells that express TCF4, KI-67, and CCR1." (PMID 37175422, 2023). "Promising markers such as 89Zr-DFO-CD4 and 89Zr-DFO-CD8a, which target CD4+ and CD8+ T cells, respectively, have the potential to identify very early histological myocarditis before the onset of clinical symptoms." (PMID 37886969, 2023). "Taken together, our model permits the determination of the roles of both CD4 and CD8 T cells to understand the disease-resistance mechanisms of myocarditis in a single transgenic system antigen-specifically." (PMID 37830560, 2023). "While CD4+ and CD8+ cell infiltration prevails in typical inflammatory myocarditis, CD68+ cell infiltration is prevalent in SARS-CoV-2-induced myocarditis." (PMID 37112659, 2023). "Specifically, monoclonal antibodies targeting CD4, CD8, and/or MHC IA/II protect against generation of myocarditis in myosin-immunized mice." (PMID 37892217, 2023). "In CCC patients, myocarditis is composed of mononuclear cells, mainly cytotoxic CD8+(granzyme A+ cells), and CD4+ T cells and macrophages." (PMID 35320825, 2022). "Deletion of both PD-1 and LAG-3 in BALB/c mice resulted in myocarditis with CD8 and CD4 cell infiltration, in addition to increased TNFα secretion." (PMID 35455289, 2022). "It expands the infiltration and accumulation of CD4+ and CD8+ T cells in the myocardium and promotes the release of myocarditis factors (such as IL-2, IL-6, etc.)." (PMID 36186992, 2022). "The distinction of leukocytes (CD45+), T lymphocytes (CD3+) and their subtypes (CD4+ or CD8+) and macrophages (CD68+) led to higher detection rates in the diagnosis of myocarditis, improving the sensitivity and specificity of the EMB." (PMID 35621854, 2022). "We decided to assess the levels of regulatory T cells, defined as CD4 + CD25 + FOXP3+ lymphocytes, from myocarditis patients and controls." (PMID 35265721, 2022). "Ctla4+/− Pdcd1−/− mice showed increased troponin levels with cardiac infiltration of CD3, CD8, and CD4 cells, and reduced numbers of Treg cells, similar to that seen in human ICI myocarditis." (PMID 35455289, 2022). "ICI-related myocarditis has been attributed to an immune infiltration, comprising of T-cells that are positive for CD3+, CD4+, CD8+, and macrophages that are positive for CD68." (PMID 34055610, 2021). "Furthermore, as a potential consequence of expanding self-antigen exposure from virus-infected cardiomyocytes or epitope cross-reactivity, CVB3 infection may increase the number of autoreactive CD4+ T cells for multiple antigens, which contributes to the development of myocarditis." (PMID 34072423, 2021). "Histopathological evaluation of endomyocardial biopsies has revealed a lymphocytic infiltrate of CD4+ and CD8+ cells in the myocardium and conducting system of patients with myocarditis." (PMID 34680365, 2021). "Both CD4+ and CD8+ T cells are recruited within a week of infection, and T cells have been shown to be important for the development of myocarditis following MCMV infection in mice." (PMID 34696354, 2021). "CD4+ T cells can play both an inflammatory and a regulatory role in the pathogenesis of EAM, as well as of myocarditis in humans." (PMID 34944410, 2021).
myocarditis (continued). "As an intracellular pathogen, T. cruzi triggers a CD4+ and CD8+ T-cell response.T cells were already described as an important actor during the development of chronic chagasic myocarditis." (PMID 31365537, 2019). "CD4+ T cells were isolated from blood and lymphoid organs of mice immunized with α-MyHC and CFA 5–7 days after immunization (before myocarditis onset) and were further stimulated ex vivo for 3–5 days with α-MyHC antigen in the presence of APCs." (PMID 31863205, 2019). "Adoptive transfer of α-MyHC-re-stimulated CD4+ T cells isolated from inguinal LNs and spleens of α-MyHC/CFA immunized wild-type donor mice expressing CD45.1+ alloantigen, effectively induced myocarditis in sub-lethally irradiated CD45.2+ wild-type recipients." (PMID 31863205, 2019). "These authors showed severe myocarditis in T. cruzi-infected mice, with intense IL-1β and TNF-α production by macrophages and IFN-γ production by CD4+ and CD8+ T cells." (PMID 30364017, 2018). "This post-infarct autoimmune (PIA) syndrome was also characterized by expansion of γ-interferon-producing CD4 T cell responses to α-MyHC, similar to the T cell responses observed in DQ8+NOD mice with spontaneous myocarditis [12••]." (PMID 25821130, 2015). "The current studies show that increased expression of c-FLIPS in T lymphocytes considerably increases CVB3-induced myocarditis and induction of autoimmune, heart-specific CD8+ effector T cells, while inhibiting CD4+ FoxP3+ T regulatory cell responses." (PMID 24816846, 2014). "Although T lymphocytes were a major cell type in both severe cChHD and GCM, the latter was enriched in macrophages/dendritic cells and CD4+ T cells, whereas CD8 was prevalent in cChHD with severe myocarditis." (PMID 25144227, 2014). "Additionally, other CD4+ cell populations may be involved in myocarditis development and outcome." (PMID 23460527, 2013). "Several reports showed that CD4+ T cells producing IFN-γ controlled the differentiation, migration and activation of macrophage lineage cells in myocarditis, central nervous system and Ang II-induced kidney injury." (PMID 22567105, 2012). "A kinetic study of heart colonization by inflammatory CD4+ and CD8+ cells, the major components of chagasic myocarditis, in T. cruzi-infected C57BL/6 mice revealed that rare mononuclear cells were detected in the cardiac tissue at 15 dpi." (PMID 22532799, 2012). "An early case report described the infiltration of CD68+ macrophages and CD4+ and CD8+ T cells into the myocardium of patients with ICI myocarditis, whereas in another case report, a predominance of CD8+ T cells was seen in the myocardium, with a decrease of Foxp3+ Treg cells." (PMID 39023770, 2025). "The spontaneous development of progressive myocarditis in transgenic mice expressing particular human MHC class II molecules supports the notion that MHC class II-dependent antigen presentation to CD4+ T cells is a key process that drives myocardial inflammation under various conditions." (PMID 39196111, 2024). "We explored whether the proportions of CD4+ and CD8+ T-cell subsets might be informative in terms of myocarditis pathogenesis and/or the severity of myocardial damage." (PMID 38398340, 2024). "Also, the deletion of PD-L1 or PD-1 in autoimmune-prone MRL-mice resulted in fatal myocarditis characterized by cardiac infiltration of CD8+ and CD4+ T cells and macrophages." (PMID 39834851, 2024). "The most common form is myocarditis involving CD4+-mediated T-cell inflammation rather than the cardiac adverse events defined in our study." (PMID 38592677, 2024). "The removal of CD8+ T cells prevented myocarditis development, while the removal of CD4+ T cells did not alter myocarditis incidences." (PMID 39465131, 2024). "Additionally, in a genetic mouse model of ICI‐related myocarditis, inflammatory cells observed in the heart comprised CD8+ T cells and a small number of CD4+ and FOXP3+ T cells." (PMID 38634742, 2024).
myocarditis (continued). "At an early stage of EAM, both adoptive transfer (AT) and selective depletion of MDSCs could inhibit the expression of IL‐17 in CD4+ cells and downregulate the Th17/Treg ratio, alleviating excessive inflammation of EAM myocarditis." (PMID 37382257, 2023). "PET radiotracers that target inflammatory cells such as CD4+, CD8+, and fibroblast activating protein (FAP), may play a crucial role in the early detection of subclinical myocarditis." (PMID 37886969, 2023). "ICI myocarditis is characterized by lymphocytic infiltration with CD4 and CD8 cells and mortality is high if not identified and if left untreated." (PMID 35369354, 2022). "Correspondingly, in both CD8+ and CD4+ T cells mediated myocarditis models, a lack of PD-1 enhanced cardiac damage." (PMID 36354777, 2022). "Moreover, among the CD4+ T cells, only CD62L− cells were able to induce myocarditis in the recipients." (PMID 33466825, 2021). "In summary, our data suggest that neither ROCK1 nor ROCK2 is critically involved in the development of CD4+ T cell-mediated myocarditis and postinflammatory fibrosis." (PMID 32178482, 2020). "The possible reason that CD4+ T-lymphocytes dominated over CD8+ T-lymphocytes in cardiac inflammatory and apoptotic response is the CD4+ T-lymphocytes’ response during the initiation and early stages of myocarditis." (PMID 32244307, 2020). "So far, however, the role of antigen-independent mechanisms and heart non-specific CD4+ T cells in myocarditis remained elusive." (PMID 31863205, 2019). "Adoptive transfer experiments showed that while heart-specific Teff infiltrated the heart shortly after injection, heart non-specific Teff effectively accumulated during myocarditis and became the major heart-infiltrating CD4+ T cell subset at later stage." (PMID 31863205, 2019). "Indeed, application of CAPs in CVB3-infected mice reduced cardiac MNC activation, increased CD4+ and CD8+ T cell apoptosis in the spleen, and raised the % of T regulatory cells, which recently have been shown to protect against CVB3-induced myocarditis." (PMID 22174827, 2011). "Immune cells such as EM DN (CD4−CD8−) %DN, TD DN (CD4−CD8−) %DN, and CD25 on CD45RA+ CD4 non-Treg cells may also act as mediators influencing the onset and progression of myocarditis." (PMID 40906170, 2025). "It has been reported that CD4 regulatory T cells can secrete regulatory cytokines (IL-10 and TGF-β) to inhibit the activities of other immunophenotypes, and thus we speculate that CD4 regulatory T cells play an important role in myocarditis." (PMID 39280093, 2024). "Additionally, T-cell involvement in postvaccine myocarditis cannot be conclusively ruled out because a slight increase in PD-1–expressing bulk CD4 + T cells suggests potential T-cell activation or exhaustion." (PMID 38360752, 2024). "In a notable investigation employing an experimental model of CVB3-induced myocarditis, the ablation of CD4 + T cells demonstrated a mitigating effect on myocardial inflammation, whereas the sole deletion of CD8 + T cells had no discernible impact on myocarditis-associated inflammation." (PMID 39075540, 2024). "Other types of CD4+ lymphocytes, such as Th22 cells, have been reported to be increased in peripheral blood of DCM patients, indicating that a broader range of T helper cells might be involved in myocarditis/DCM pathogenesis." (PMID 39768171, 2024). "In the present study, the infiltration of CD4+ T-cells into the myocardium of mice increased following the administration of a PD-1 inhibitor, suggesting that the modulation of CD4+ T-cells may provide a novel therapeutic direction for ICI-related myocarditis." (PMID 38236243, 2024). "When CD4+ T cells were the only ones to be removed, myocarditis incidences did not change." (PMID 37260696, 2023).
myocarditis (continued). "Appendectomy significantly decreased intestinal IL-10 and IL-10+ CD4+ Treg frequency which led to a marked increase in intestinal (primary entry site for CVB3) anti-viral IFN-γ+ CD4+ T and IFN-γ+ CD8+ T response and viral restriction, eventually resulting in improved myocarditis." (PMID 37896753, 2023). "However, there is currently not sufficient data regarding the explicit roles of CD4 or CD8 T-cells in ICI-induced myocarditis." (PMID 36979163, 2023). "Furthermore, impaired negative selection of CD4+ T-cells specific for the alpha-myosin heavy chain in the thymus of mice and humans has led to the development of myocarditis." (PMID 36979163, 2023). "It has been demonstrated that ONX 0914 reduces the activation of CD4+ T cells by restraining ERK signaling and inducing proteostatic stress in vitro and that CD4+ T cell activation was reduced upon ONX 0914 treatment in a mouse model of myocarditis, suggesting a similar mechanism in our setting." (PMID 35711460, 2022). "Because CD4+ T cells were increased by BPA exposure in drinking water, we examined whether IFNγ, IL-4, and/or IL-17A cytokine levels were altered in the heart during acute CVB3 myocarditis following BPA exposure." (PMID 31551929, 2019). "From this point of view, and given the antifibrotic and cardioprotective properties of heart non-specific Teff, significant infiltrations with CD4+ T lymphocytes could even indicate favourable outcome in myocarditis." (PMID 31863205, 2019). "All four patients with active myocarditis exhibited very mild infiltration of CD4+, CD8+, and CD20+ lymphocytes, and single or small clusters of CD68+ macrophages, and this pattern was also evident in all 22 patients without active myocarditis." (PMID 36312241, 2022). "Our experiments do not formally exclude contributions of CD4 T cells or non-memory CD8 T cells to protection in vaccinated mice, but the data support the likely possibility that vaccine-induced memory CD8 T cells protect against CVB3-induced myocarditis." (PMID 28642849, 2017).